ENSG00000266086 (novel transcript)
Gene: Protein-coding gene on chromosome 17 (57,989,038 to 58,007,246, reverse strand). Ensembl gene ENSG00000266086.
Genetic constraint (gnomAD): Missense variants: 71 observed, 303.87 expected, observed/expected ratio (o/e) 0.23, 90% interval 0.19 to 0.28. Synonymous variants: 116 observed, 111.49 expected, observed/expected ratio (o/e) 1.04, 90% interval 0.89 to 1.21.